TBXA2R (thromboxane A2 receptor)
Description:
Receptor for thromboxane A2 (TXA2), a potent stimulator of platelet aggregation. The activity of this receptor is mediated by a G-protein that activates a phosphatidylinositol-calcium second messenger system. In the kidney, the binding of TXA2 to glomerular TP receptors causes intense vasoconstriction. Activates phospholipase C. [Isoform 1]: Activates adenylyl cyclase. [Isoform 2]: Inhibits adenylyl cyclase.
Synonyms: TXA2-R; BDPLT13
Tractability: Small molecule: an approved drug acts on it; a structure with a bound ligand is known; a high-quality ligand is known; it belongs to a druggable protein family. Antibody: its Gene Ontology location is reachable by antibodies, with high confidence; UniProt places it where antibodies can reach, with medium confidence; UniProt predicts a signal peptide or a membrane-spanning region; the Human Protein Atlas places it where antibodies can reach. PROTAC: a small molecule that binds it is known.
Target class: Lipid-like ligand receptor (family A GPCR); Membrane receptor; Prostanoid receptor; Small molecule receptor (family A GPCR); Family A G protein-coupled receptor
Safety:
Unwanted effects reported when the protein is acted on. In parentheses: how it was acted on, where the effect was seen, and who reports it.
bronchoconstriction (activation; cardiovascular system; source: Urban et al. (2012))
heart failure (activation; cardiovascular system; source: Urban et al. (2012))
inhibition platelet aggregation (inhibition; cardiovascular system; source: Urban et al. (2012))
myocardial ischemia (activation; cardiovascular system; source: Urban et al. (2012))
platelet aggregation (activation; cardiovascular system; source: Urban et al. (2012))
vasoconstriction (activation; cardiovascular system; source: Urban et al. (2012))
aspirin-intolerant asthma (source: ClinPGx)
mortality (source: ClinPGx)
Gene: Protein-coding gene on chromosome 19 (3,594,506 to 3,606,895, reverse strand). Ensembl gene ENSG00000006638.
Subcellular location: Cell membrane
Subcellular location (Human Protein Atlas): Plasma membrane; Nuclear speckles
Pathways (Reactome):
Signal Transduction: G alpha (12/13) signalling events; G alpha (q) signalling events; Prostanoid ligand receptors
Hemostasis: Thromboxane signalling through TP receptor
Gene Ontology:
Molecular function: protein binding; guanyl-nucleotide exchange factor activity; thromboxane A2 receptor activity; G protein-coupled receptor activity; thromboxane receptor activity
Biological process: negative regulation of cell migration involved in sprouting angiogenesis; adenylate cyclase-activating G protein-coupled receptor signaling pathway; G protein-coupled receptor signaling pathway; inflammatory response; positive regulation of blood pressure; positive regulation of cytosolic calcium ion concentration; positive regulation of vasoconstriction; cellular response to lipopolysaccharide; positive regulation of angiogenesis; positive regulation of blood coagulation; response to ethanol; response to nutrient; response to testosterone; response to xenobiotic stimulus; thromboxane A2 signaling pathway
Cellular component: plasma membrane; acrosomal vesicle; membrane
Genetic constraint (gnomAD): Loss-of-function variants: 15 observed, 15.57 expected, observed/expected ratio (o/e) 0.96, 90% interval 0.64 to 1.48. The upper end of that interval is the gene's LOEUF score, 1.48, which puts it in group 6 of 6, group 1 being the genes least tolerant of losing a copy. Missense variants: 506 observed, 499.7 expected, observed/expected ratio (o/e) 1.01, 90% interval 0.94 to 1.09. Synonymous variants: 280 observed, 246.63 expected, observed/expected ratio (o/e) 1.14, 90% interval 1.03 to 1.25.
Gene-disease validity (ClinGen):
ClinGen rates the evidence that TBXA2R causes each of these diseases.
qualitative platelet defect (autosomal dominant): Moderate.
Homologues: Orthologues: chimpanzee TBXA2R (99% identical), macaque TBXA2R (97% identical), dog TBXA2R (86% identical), pig TBXA2R (84% identical), guinea pig TBXA2R (77% identical), mouse Tbxa2r (75% identical), rat Tbxa2r (74% identical), tropical clawed frog tbxa2r (55% identical), zebrafish tbxa2r (25% identical), Drosophila melanogaster CG7497 (20% identical). Paralogues in human: PTGER1 (36% identical), PTGFR (33% identical), PTGER3 (31% identical), PTGIR (27% identical), PTGER4 (24% identical), PTGDR (24% identical), PTGER2 (24% identical).
Diseases named in the same sentence as TBXA2R in open-access papers:
TBXA2R is named in the same sentence as 72 diseases in open-access papers, as found by Europe PMC text mining. Sharing a sentence is not in itself a finding about the gene and the disease. The quoted sentences say what the papers report.
asthma (7 papers, 2016 to 2024). "The present study provided several lines of evidence to support that TBXA2R rs34377097 polymorphism act as a potent risk factor for asthma in West Bengal population, India." (PMID 36936944, 2023). "The present study aimed to assess potential association of TBXA2R rs34377097 polymorphism causing missense substitution of Arginine to Leucine (R60L) among 482 patients diagnosed with pollen-induced asthma and 122 control participants from West Bengal, India." (PMID 36936944, 2023). "The minor allele at two of the SNPs showed association with protection from asthma, rs1131882 in TBXA2R gene (OR 0.73, 95% CI 0.52–1.01, P = 0.05) and rs2280091 in the ADAM33 gene (OR 0.69, 95% CI 0.50–0.97, P = 0.03)." (PMID 29588858, 2018). "In a study of other variants in this gene in Japanese subjects, TBXA2R alleles were also associated with asthma-related phenotypes." (PMID 29588858, 2018). "One of the causative agents of broncho-constriction in asthma is thromboxane A2 receptor (TBXA2R)." (PMID 36936944, 2023). "We have found an association between rs1131882 (TBXA2R) and asthma in Pakistani population." (PMID 29588858, 2018). "This study investigated associations between asthma and a TBXA2R polymorphism." (PMID 29588858, 2018). "In addition, these observations raise the possibility that polymorphisms in the TBXAS1 or the TBXA2R gene may be associated with altered asthma risk in humans." (PMID 38483511, 2024). "Evidence suggested that in absence of TBXA2, LTC4 synthase activity is enhanced through its receptor (TBXA2R), resulting in increased leukotriene biosynthesis and asthma symptoms." (PMID 36936944, 2023). "In our study, we found significant association of rs34377097 polymorphic TT genotype in the exon-2 region of the TBXA2R gene with elevated pollen induced asthma response such as acute broncho and tracheal constriction in West Bengal population, India." (PMID 36936944, 2023). "The present study suggests that variations at TBXA2R and ADAM33 genes are linked with asthma susceptibility in Pakistan." (PMID 29588858, 2018). "It is not only an antioxidant, but also a blocker of the thromboxane A2 receptor and is used in the treatment of asthma." (PMID 28867994, 2017). "A good example of these is 8-epi-prostaglandin F2 alpha (8-epi-PGF2 alpha), which has also been shown to cause contraction of smooth muscle by triggering the thromboxane A2 receptor (TBXA2R), and has been shown to have a role in asthma and EIA." (PMID 27524866, 2016). "A recent meta-analysis of 7 studies concluded that the TBXA2R 924C/T polymorphism is associated with asthma risk and the TBXA2R795C/T polymorphism may be a risk factor for aspirin-intolerant asthma." (PMID 38483511, 2024). "Literature suggested that TBXA2R pathway play a significant role in asthma." (PMID 36936944, 2023). "Finally, eight potentially important small molecules targeting asthma were screened by the cMAP database, and seven of them had significant correlation with TBXA2R." (PMID 35619697, 2022).
breast carcinoma (7 papers, 2005 to 2025). "Most likely, TBXA2R up-regulation might be implicated in modulating angiogenesis during chronic inflammation and tumor growth and thus ubiquitous in human breast cancer." (PMID 29872696, 2017). "In summary, TBXA2R is a novel breast cancer-associated gene required for the survival and migratory behaviour of a subset of TNBCs and could provide opportunities to develop novel, more effective treatments." (PMID 27487152, 2016). "We suggest that the emergence of aggressive phenotypes observed following loss of BRCA1 function in breast cancer cells may be partly due to the de-repression of TBXA2R." (PMID 27487152, 2016). "Furthermore, TBXA2R levels are associated with disease free survival, indicating that the receptor is a prognostic factor in clinical breast cancer." (PMID 16250911, 2005). "In two recent reports that TBXA2R is dysregulated in breast cancers, malignancy was contributed primarily to increases in tumor cell proliferation, migration, or invasion." (PMID 41233835, 2025). "Next, we established orthotopic mammary tumors with TBXA2R-deleted 4T1 tumor cells (TPr KO 4T1 cells) and commenced treatment with ifetroban under the same protocol." (PMID 41233835, 2025). "Because TXA2 is known to function through the activation of the thromboxane A2 receptor (TBXA2R), we further investigated TBXA2R expression in breast cancer and observed that the protein levels of TBXA2R in breast tumors were 5.9-fold higher than NAT." (PMID 29872696, 2017). "During the immunohistochemical study, we noticed that positive regions of TBXAS1 or TBXA2R immunostaining were mainly in mammary ducts from where primary breast cancer is believed to arise." (PMID 29872696, 2017). "Using publically available gene expression data we observed that TBXA2R (as predicted given that it is a basally restricted marker) represents a poor prognosis marker of breast cancer overall using KM plotter (p = 0.038, HR 1.84)." (PMID 27487152, 2016). "In this study, we have identified TBXA2R as a novel survival factor for breast cancer which specifically maintains cell viability of TNBC cells." (PMID 27487152, 2016). "In the current study, we have investigated the level of expression of Thromboxane A synthase 1, TBXAS1 (otherwise known as Cyp5 and TXS) and Thromboxane A2 receptor, TBXA2R, in a cohort of human breast cancer patients." (PMID 16250911, 2005). "TBXA2R thus has a significant prognostic value in clinical breast cancer." (PMID 16250911, 2005). "In addition, TBXA2R has also been involved in the migration and invasion of breast cancer cells." (PMID 31905626, 2019). "Therefore, it is reasonable to propose that the observed effects of PhytoPs and PhytoFs on cellular survival and proliferation in the present work could be related to their ability to regulate TBXA2R function in breast cancer cells." (PMID 31905626, 2019). "The aim of the study was to investigate the expression of thromboxane synthases, TBXAS1 and the thromboxane A2 receptor, TBXA2R in a cohort of human breast cancer patients and also to assess their potential clinical relevance." (PMID 16250911, 2005). "Although a high level of TBXA2R was seen in patients who died of breast cancer, this was not significant." (PMID 16250911, 2005). "In cancer cells, including breast cancer cells, TBXA2R has been shown not to influence the adhesion of cancer cells to matrix proteins." (PMID 16250911, 2005). "We detected two receptors uniquely expressed in all breast cancer cell lines but not in control cells: GPRC5B (a Class-C orphan receptor, ΔCt = 17.8) and TBXA2R (thromboxane A2 receptor, ΔCt = 19.4)." (PMID 29872392, 2018). "TBXA2R mRNA expression was then measured in a panel of breast cell lines by quantitative real time PCR (qPCR), showing that TBXA2R expression is specifically elevated in TNBC cell lines relative to non-tumorigenic breast, HER2-overexpressing or luminal breast cancer lines." (PMID 27487152, 2016).
ischemic stroke (6 papers, 2016 to 2024). A stroke disorder caused by obstruction of blood flow to the brain, due to thrombotic (local blood clot formation) or embolic (due to a blood clot or other material traveling from another site) event. "Polymorphisms in Tbxa2r were associated with higher blood pressure, platelet aggregation and ischemic stroke." (PMID 36077596, 2022). "In our study, we revealed the association between clinical parameters (age, NIHSS score, atrial fibrillation), as well as SNPs in the PTGS1, ADRA2A, TBXA2R and PEAR1 genes, and laboratory indicators of platelet activity in ischemic stroke patients taking aspirin for secondary stroke prevention." (PMID 36289824, 2022).
breast tumours (5 papers, 2005 to 2022). "The knockdown of TBXAS1 (the rate-limiting enzyme involved in TXA2 biosynthesis) and TBXA2R (TXA2 receptor) both of which are overexpressed in breast tumours, reduced the colony formation and proliferation of hormone-dependent breast tumour cell lines." (PMID 36558983, 2022). "Breast tumour tissue expressed higher levels of TBXA2R compared with normal mammary tissues, although the difference was not statistically significant (p = 0.09)." (PMID 16250911, 2005). "Additionally, analysis of TBXA2R mRNA levels in 120 human breast tumours and 32 non-cancerous mammary tissues showed higher levels of TBXA2R transcript were significantly associated with higher grade tumours and shorter disease free survival." (PMID 27487152, 2016). "Immunohistochemical analysis revealed that either thromboxane A2 synthase 1 or the thromboxane A2 receptor is highly expressed in human breast tumors as well as premalignant lesions, but not in normal mammary tissues." (PMID 29872696, 2017).
Stroke (5 papers, 2016 to 2025). Sudden impairment of blood flow to a part of the brain due to occlusion or rupture of an artery to the brain. "The prothrombotic effects of testosterone, such as increasing hematocrit levels, platelet aggregation, and thromboxane A2 receptor density on platelets, are well-established and may contribute to cardiovascular events such as MI and stroke." (PMID 39906442, 2025). "Additionally, using salt loaded stroke-prone spontaneously hypertensive rats, pharmacological inhibition of TBXA2R was shown to reduce oxidative stress, Hypoxia-inducible factor-1 expression and renal glomerular and tubulointerstitial damage." (PMID 36077596, 2022).
triple-negative breast carcinoma (4 papers, 2016 to 2026). An invasive breast carcinoma which is negative for expression of estrogen receptor (ER), progesterone receptor (PR), and human epidermal growth factor receptor 2 (HER2). "We identified the thromboxane A2 receptor (TBXA2R), a G protein-coupled receptor overexpressed in multiple cancers, as a critical activator of ERMs, enhancing the motility and invasion of triple-negative breast cancer cells." (PMID 41844278, 2026). "Furthermore, we demonstrate that TBXA2R promotes triple-negative breast cancer cell motility and invasion in vitro and metastatic colonization in vivo, dependent on ERM function." (PMID 41844278, 2026). "Notably, increased expression of TBXA2R was observed in human breast cancer tumors, and activation of this receptor promoted the proliferation of lung carcinoma cells and survival of triple-negative breast cancer cells." (PMID 31905626, 2019).
atherosclerosis (3 papers, 2017 to 2025). A disease characterized by the build-up of fatty material and calcium deposition in the arterial wall resulting in partial or complete occlusion of the arterial lumen. "TBXA2R, located on chromosome 19:3,594,507–3,606,875 reverse strand, may affect platelet function and venous thrombosis, platelet aggregation, and the process of atherosclerosis." (PMID 32723322, 2020).
colorectal cancer (3 papers, 2015 to 2023). A primary or metastatic malignant neoplasm that affects the colon or rectum. "The knockdown of TBXA2R (TP receptor) or TBXAS1 (TXS) in human colorectal cancer cells results in fewer colonies being formed in soft agar than in control cells." (PMID 37173923, 2023). "Based on this idea, we confirmed that knockdown of TBXA2R or TBXAS1 in human colorectal cancer cells resulted in fewer colonies being formed in soft agar compared with control cells." (PMID 25750933, 2015).
COVID-19 (3 papers, 2021 to 2023). A disease caused by infection with severe acute respiratory syndrome coronavirus 2. "The receptor for thromboxane A2 (TBXA2R), a potent stimulator of platelet aggregation, was detected as EP in the COVID-19 and survivor groups." (PMID 35842415, 2022). "Crucially, platelet activation with the thromboxane A2 receptor agonist U46619 (1 μM) induced a 28-fold increase in ADP-release in COVID-19–positive patients compared to HeC and strikingly, an 89-fold increase between COVID-19–positive patients and HoC." (PMID 33596198, 2021). "Comprising platelet activation, coagulation and wound healing GO terms and platelet-associated genes such as MYL9, ITGB3, GP1BB, TBXA2R and GP6, expression of the Magenta module increased modestly over time and was consistently higher in patients with severe COVID-19." (PMID 37365222, 2023).
glioma (3 papers, 2005 to 2024). A benign or malignant brain and spinal cord tumor that arises from glial cells (astrocytes, oligodendrocytes, ependymal cells). "High levels of TBXA2R and TBXA2Rs have been previously reported in various tumours including prostate, glioma, and melanoma." (PMID 16250911, 2005). "Among the individual genes, F3, F7, and TBXA2R showed higher expression densities in glioma cells." (PMID 38955935, 2024). "TBXA2R is usually expressed in tumors, especially in invasive tumors, which has a potential effect on the metastasis of cancer cells through its metabolite TAX2, which has previously been reported to be found in various tumors, including prostate, glioma, and melanoma." (PMID 31569385, 2019).
melanoma (3 papers, 2005 to 2025). A malignant, usually aggressive tumor composed of atypical, neoplastic melanocytes. "TBXA2R-null platelets aggregate poorly with tumor cells when co-cultured ex vivo, fail to accumulate at sites of lung metastasis, and express lower levels of P-selectin and integrins, resulting in reduced metastases after intravenous injection of B16-F1 melanoma cells in TBXA2R-null animals." (PMID 41233835, 2025).
colon cancer (2 papers, 2015 to 2022). "Knockdown of either TBXAS1 or TBXA2R impairs the anchorage-independent growth capability of colon cancer cells." (PMID 25750933, 2015). "In addition, aspirin treatment down-regulated TBXA2R or TBXAS1 expression in colon cancer cells." (PMID 25750933, 2015).
heart failure (2 papers, 2014 to 2021). Inability of the heart to pump blood at an adequate rate to meet tissue metabolic requirements. "We demonstrate that thromboxane A2 receptor signaling within the sensory endings of thin fiber muscle afferents of rats with heart failure with reduced ejection fraction (HF‐rEF) contributes to an exaggerated exercise pressor reflex (EPR) evoked during dynamic hindlimb skeletal muscle contractions." (PMID 34558221, 2021).
ischemia (2 papers, 2016 to 2022). A hypoperfusion of the BLOOD through an organ or tissue caused by a PATHOLOGIC CONSTRICTION or obstruction of its BLOOD VESSELS, or an absence of BLOOD CIRCULATION. "In ischemia/reperfusion mice, increased Thromboxane A2 receptor (TXA2R) expression was detected in microglia/macrophages by double staining with immunofluorescence, and the TXA2R antagonist SQ29548 inhibited M1 microglia activation and subsequent inflammatory response." (PMID 35356292, 2022).
lung adenocarcinoma (2 papers, 2013 to 2022). A carcinoma that arises from the lung and is characterized by the presence of malignant glandular epithelial cells. "We found that TGFB1, ENG, TGM2, TBXA2R, HSPG2, and PTPRS were significantly upregulated in lung adenocarcinoma cells." (PMID 36249427, 2022). "Two other important genes i.e. GRM2 and TBXA2R in Merged-module being from the GPCR superfamily, showed over-expression in lung adenocarcinoma." (PMID 23874428, 2013).